NOSIP (nitric oxide synthase interacting protein)
Description:
E3 ubiquitin-protein ligase that is essential for proper development of the forebrain, the eye, and the face. Catalyzes monoubiquitination of serine/threonine-protein phosphatase 2A (PP2A) catalytic subunit PPP2CA/PPP2CB (By similarity). Negatively regulates nitric oxide production by inducing NOS1 and NOS3 translocation to actin cytoskeleton and inhibiting their enzymatic activity.
Synonyms: CGI-25
Tractability: Small molecule: a structure with a bound ligand is known. PROTAC: ubiquitination databases record sites on it; its protein half-life has been measured.
Target class: Enzyme; Transferase
Gene: Protein-coding gene on chromosome 19 (49,555,468 to 49,592,927, reverse strand). Ensembl gene ENSG00000142546.
Subcellular location: Cytoplasm; Nucleus
Subcellular location (Human Protein Atlas): Nucleoplasm
Pathways (Reactome):
Metabolism: NOSIP mediated eNOS trafficking
Gene Ontology:
Molecular function: molecular sequestering activity; protein binding; RNA binding; ubiquitin protein ligase activity
Biological process: negative regulation of catalytic activity; negative regulation of nitric-oxide synthase activity; regulation of nitric oxide biosynthetic process; nitric oxide metabolic process
Cellular component: cytoplasm; nucleoplasm; nucleus; cytosol; Golgi membrane; actin cytoskeleton
Genetic constraint (gnomAD): Loss-of-function variants: 24 observed, 29.8 expected, observed/expected ratio (o/e) 0.81, 90% interval 0.58 to 1.13. The upper end of that interval is the gene's LOEUF score, 1.13, which puts it in group 4 of 6, group 1 being the genes least tolerant of losing a copy. Missense variants: 369 observed, 418.76 expected, observed/expected ratio (o/e) 0.88, 90% interval 0.81 to 0.96. Synonymous variants: 185 observed, 179.26 expected, observed/expected ratio (o/e) 1.03, 90% interval 0.92 to 1.17.
Homologues: Orthologues: chimpanzee NOSIP (99% identical), macaque NOSIP (99% identical), dog NOSIP (94% identical), guinea pig NOSIP (92% identical), rat Nosip (92% identical), mouse Nosip (91% identical), pig NOSIP (79% identical), tropical clawed frog nosip (72% identical), rabbit NOSIP (68% identical), zebrafish nosip (65% identical), Drosophila melanogaster CG6179 (48% identical), Caenorhabditis elegans R05G6.4 (44% identical).
Diseases named in the same sentence as NOSIP in open-access papers:
NOSIP is named in the same sentence as 13 diseases in open-access papers, as found by Europe PMC text mining. Sharing a sentence is not in itself a finding about the gene and the disease. The quoted sentences say what the papers report.
behavioral disorders (2 papers, 2017 to 2025). "In addition, differentially methylated CG dinucleotides in LRP2BP, TOP1, NOSIP, and SEMA4B were associated with intellectual disability, behavioral disorders, disorders of psychological development, and schizophrenia spectrum disorders, respectively." (PMID 39460848, 2025).
asthma (1 paper, 2021). "The association of NOSIP and DGKB with biomarker levels of the workers in our study provides novel evidence that NOS and nitric oxide may be impacting the toxicokinetics of isocyanates even before asthma development." (PMID 34335698, 2021).
atherosclerosis (1 paper, 2021). A disease characterized by the build-up of fatty material and calcium deposition in the arterial wall resulting in partial or complete occlusion of the arterial lumen. "According to model 1, the honeydew module had 31 genes significantly and jointly associated with early traits of both osteoporosis (DRToBMC) and atherosclerosis (BIMTmax), the most significant (p.adj = 7.4 × 10−16) being Nitric Oxide Synthase Interacting Protein (NOSIP)." (PMID 33782480, 2021).
breast carcinoma (1 paper, 2023). "Similar to NOSIP in pancreatic cancer, Ring Finger Protein 130 (RNF130) was highly expressed in breast invasive carcinoma (BRCA) in TCGA and was also highly expressed in 11 of 12 breast cancer samples in HPA pathology." (PMID 37845222, 2023).
holoprosencephaly (1 paper, 2014). Holoprosencephaly (HPE) is a complex brain malformation resulting from incomplete cleavage of the prosencephalon, occurring between the 18th and 28th day of gestation, and affecting both the forebrain and face, which results in neurological manifestations and facial anomalies of variable severity. "The loss of NOSIP in mice causes holoprosencephaly and facial anomalies including cleft lip/palate, cyclopia and facial midline clefting." (PMID 25546391, 2014). "We conclude, that NOSIP is a critical modulator of brain and craniofacial development in mice and a candidate gene for holoprosencephaly in humans." (PMID 25546391, 2014).
pancreatic adenocarcinoma (1 paper, 2023). "For example, Nitric Oxide Synthase Interacting Protein (NOSIP) was highly expressed in pancreatic adenocarcinoma (PAAD) in TCGA and was also highly expressed in 10 of 11 pancreatic cancer samples in HPA pathology." (PMID 37845222, 2023).
cancer (2 papers, 2021 to 2022). A tumor composed of atypical neoplastic, often pleomorphic cells that invade other tissues. "Similarly, also the interactions existing between NOS1 and NOSIP have been investigated; however, the functional effects of these interactions in cancer are not fully understood yet." (PMID 35740092, 2022).
tumor (1 paper, 2022). "Specifically, we observed that the authority score of key genes in tumor recognition, such as GZMB, NOSIP and multiple HLA family genes, were significantly incremented in D12." (PMID 35414121, 2022).
NOSIP also shares sentences with these, for which no sentence is quoted: disorders of psychological development (2 papers); Intellectual disability (2); breast invasive carcinoma (1); osteoporosis (1); pancreatic cancer (1).